SAMD13 (sterile alpha motif domain containing 13)
Synonyms: HSD-42; DJL; HSD-41
Tractability: No criterion of Open Targets' tractability assessment is met for any kind of drug.
Gene: Protein-coding gene on chromosome 1 (84,298,366 to 84,389,957, forward strand). Ensembl gene ENSG00000203943.
Subcellular location (Human Protein Atlas): Mitochondria
Genetic constraint (gnomAD): Loss-of-function variants: 3 observed, 7.51 expected, observed/expected ratio (o/e) 0.4, 90% interval 0.18 to 1.03. That is too few expected variants to judge how well the gene tolerates losing a copy. Missense variants: 61 observed, 101.25 expected, observed/expected ratio (o/e) 0.6, 90% interval 0.49 to 0.75. Synonymous variants: 39 observed, 42.32 expected, observed/expected ratio (o/e) 0.92, 90% interval 0.71 to 1.2.
Homologues: Orthologues: chimpanzee SAMD13 (100% identical), macaque SAMD13 (100% identical), dog SAMD13 (99% identical), guinea pig SAMD13 (97% identical), pig SAMD13 (97% identical), mouse Samd13 (94% identical), rat Samd13 (80% identical), tropical clawed frog samd13 (75% identical), Caenorhabditis elegans mbtr-1 (18% identical), Drosophila melanogaster Sfmbt (16% identical), Caenorhabditis elegans lin-61 (14% identical). Paralogues in human: SAMD1 (53% identical), SCML4 (32% identical), SFMBT2 (32% identical), SCMH1 (31% identical), SFMBT1 (31% identical), PHC1 (30% identical), PHC2 (30% identical), SAMD11 (30% identical), SCML2 (30% identical), PHC3 (29% identical), L3MBTL4 (28% identical), SAMD7 (27% identical), and 6 more.
Diseases named in the same sentence as SAMD13 in open-access papers:
SAMD13 is named in the same sentence as 20 diseases in open-access papers, as found by Europe PMC text mining. Sharing a sentence is not in itself a finding about the gene and the disease. The quoted sentences say what the papers report.
bone cancer (1 paper, 2023). A primary or metastatic malignant neoplasm affecting the bone or articular cartilage. "SAMD13 was upregulated in blood, brain, liver, and bone cancers, while downregulated in colon, breast, kidney, head and neck, tongue, thyroid, adrenal gland, pharynx, testis, and endometrial cancers." (PMID 37968735, 2023).
breast carcinoma (1 paper, 2023). "Only one study showed that SAMD13 is negatively associated with invasive micropapillary carcinoma of breast cancer, especially micropapillary area, but its clinical impact on cancers remains totally unclear, even contrary." (PMID 37968735, 2023).
Cirrhosis (1 paper, 2023). A chronic disorder of the liver in which liver tissue becomes scarred and is partially replaced by regenerative nodules and fibrotic tissue resulting in loss of liver function. "Interestingly, increased mRNA expression of SAMD13 was also revealed in the cirrhosis group at GSE25097." (PMID 37968735, 2023).
hepatocellular carcinoma (1 paper, 2023). A malignant tumor that arises from hepatocytes. "This study suggested that SAMD13 expression is relevant to the pathological features and immune microenvironment in IMPC; however, the expression profile and biological role of SAMD13 in hepatocellular carcinoma remain totally unknown." (PMID 37968735, 2023).
carcinoma (2 papers, 2021 to 2023). A malignant tumor arising from epithelial cells. "Since SAMD13 gene expression was not only upregulated in various carcinomas but also linked to worst prognosis in HCC, we further performed validation on additional three independent GEO data sets." (PMID 37968735, 2023). "Although SAMD13 is highly expressed in various types of cancer, it was significantly associated with shorter OS, DSS, DFI, and PFI in patients with HCC, even poorly differentiated HCC cell lines which tend to be more aggressive and higher grade." (PMID 37968735, 2023). "It was revealed that SAMD13 was mainly expressed in scar-associated macrophages (SAMs), T cells, tumor-associated macrophages (TAMs), tumor-associated endothelial cells (TECs), and carcinoma cells, while moderately expressed in hepatocytes and cholangiocytes." (PMID 37968735, 2023). "This study aimed to explore the expression profile and prognostic effects of SAMD13 using pan-cancer database and various bioinformatics in patients with HCC." (PMID 37968735, 2023). "SAMD13 was found to be highly expressed pan-cancer; however, the SAMD13 expression was significantly correlated with the worst prognosis in HCC." (PMID 37968735, 2023). "As high-grade (poorly differentiated) cancer cells tended to be more motile and aggressive than well-differentiated cancer cells, we confirmed that mRNA expression of SAMD13 in well- and poorly differentiated HCC cell lines." (PMID 37968735, 2023). "To explore the expression pattern of SAMD13between tumor and normal tissues in various types of cancer, we examined the SAMD13 differences using the UALCAN database." (PMID 37968735, 2023). "More importantly, SAMD13 expression could be a potential for immuno-checkpoint inhibitor (ICI) treatment, although it exhibits acquired diverse anti-cancer drug resistant in HCC." (PMID 37968735, 2023). "Collectively, these results suggest that SAMD13 expression might not be involved in chemotherapy response to cancer treatment, but rather a target for ICB treatment that can counter acquired chemical resistance." (PMID 37968735, 2023). "The remaining signature genes, CPXM2, ENPP5, SAMD13, SLC52A1, ZNF682, ZNF835, ZNF571-AS1 and U91328.1, have not been related to carcinoma, yet." (PMID 33672117, 2021).
tumor (2 papers, 2023 to 2024). "In this study, our findings revealed that the level of SAMD13 expression was significantly up-regulated in the tumor group compared to the non-tumor group, while high level of SAMD13 expression was significantly associated with the worst prognosis in HCC." (PMID 37968735, 2023). "Based on tumor grade, a significant increase in SAMD13 levels was observed in the HCC group in all tumor grades." (PMID 37968735, 2023). "The correlation between SAMD13 and tumor-infiltrating immune cells in the tumor microenvironment of HCC was also determined." (PMID 37968735, 2023). "According to tumor stage, SAMD13 expression were significantly upregulated in HCC group classified as stage I to stage III compared to the corresponding normal group." (PMID 37968735, 2023). "Clinicopathological analysis revealed that SAMD13 upregulation was significantly associated with advanced HCC stage and high-grade tumor type." (PMID 37968735, 2023). "In the TCGA-HCC dataset, 13 genes were identified with significant correlation with SAMD13 from the tumor group only and a total of six genes including FOXM1, JUN, JARID2, BRE, BUB1B, and PHC2 were shown to significantly predict poor overall survival in log-rank tests in HCC." (PMID 37968735, 2023). "As expected, these GEO data sets also revealed the significant augmentation of SAMD13 mRNA expression in the tumor group compared to their normal/non-tumor group." (PMID 37968735, 2023). "Notably, genes such as NRG1, SAMD13, MFAP3L, SALL1, ZNF704, SEMA5A, and HLA-DQB1 were identified as having altered expression patterns, potentially reflecting the diverse roles of FGFRS in tumor biology." (PMID 39676867, 2024).
SAMD13 also shares sentences with these, for which no sentence is quoted: breast invasive carcinoma (1 paper); cholangiocarcinoma (1); colon adenocarcinoma (1); endometrial cancer (1); glioblastoma multiforme (1); head and neck squamous cell carcinoma (1); kidney chromophobe (1); lung adenocarcinoma (1); prostate adenocarcinoma (1); rectum adenocarcinoma (1); stomach adenocarcinoma (1); thymoma (1); thyroid carcinoma (1); uterine corpus endometrial carcinoma (1).